FASN (fatty acid synthase)
Diseases named in the same sentence as FASN in open-access papers (continued):
Sharing a sentence is not in itself a finding about the gene and the disease.
tumor (continued). "Hence, the ability of DENSPM to simultaneously suppress FASN, SCD, and FADS2 could be of critical importance for successful tumor treatment." (PMID 39337514, 2024). "Lower expression levels of FASN and ACLY may reduce citrate catabolism and generate a massive deregulation of de novo lipogenesis pathway, increasing gemcitabine uptake and improving tumor response." (PMID 38425123, 2024). "Conversely, FASN increased the level of FFA and in particular, that of PA, to increase the polarization of M2 macrophages and inhibit the infiltration of CD8+ T cells, thus promoting HCC progression through the construction of an exhausted tumor immune microenvironment." (PMID 39005234, 2024). "Finally, the expression of FASN was reduced in the orlistat group, which, however, did not result in a higher apoptosis or proliferation rate in the treatment group at the time of tumor harvesting." (PMID 38672673, 2024). "Of note, we observed that dual FASN and HER2 blockade significantly increased in vitro and in vivo therapeutic benefits by decreasing the GFE% of T-refractory cell models and by reducing tumor growth in mice implanted with highly refractory GTR0455 GC cells versus T-based monotherapy." (PMID 36753044, 2023). "Certainly, FASN inhibitors are not universal, there are differences in sensitivity to different metabolic inhibitors and in metabolic characteristics of different tumors and different subtypes of the same tumor." (PMID 37056351, 2023). "Notably, FASN and TOP1 are known as tumor promoting factors and biomarkers of a poor prognosis." (PMID 37587470, 2023). "In addition, silencing of CD147 also down-regulated FASN and ACOX1 in tumor tissues (P < 0.01)." (PMID 37880644, 2023). "Modulating the expression of ACLY and FASN through SREBP1 affects de novo lipogenesis production in PRAD cells, promoting cell proliferation, which is consistent with the inhibitory effects observed upon ACLY knockdown in NPC and PRAD that inhibit tumor cell migration and growth." (PMID 38189049, 2023). "Tumor cells undergo lipid metabolic reprogramming through de novo lipogenesis involving key transcription factors such as sterol regulatory element binding protein (SREBP), ATP citrate lyase (ACLY), acetyl-CoA carboxylase (ACC), fatty acid synthase (FASN) and stearoyl-CoA desaturase 1 (SCD1)." (PMID 38189049, 2023). "However, the function of FASN in various human malignancies and its correlation with tumor immunity have not been well characterized." (PMID 36555243, 2022). "In addition, the FASN expression levels were significantly correlated with the clinical grade and stage of various tumors, especially in KIRP, KIRC, TGCT, and CESC, and the expression of FASN was increased with tumor progression." (PMID 36555243, 2022). "Although the new FASN inhibitors TVB-2640, TVB-3664, TVB-3166, TVB-3664, and TVB-3166 showed high specificity and superior anti-tumor activity as specific FASN inhibitors, their clinical research is still in the early stages, and have not been broadly applied in tumor therapy." (PMID 36555243, 2022). "We speculate that the significance of co-enzyme A, glyceryl tripalmitoleate and oleic acid in stratifying the samples based on Gleason score, could be due to elevated expression of fatty acid synthase (FAS), which has been previously postulated to be a marker of tumour aggressiveness." (PMID 36068275, 2022). "A recent study revealed that FASN has a higher expression in the HER2 positive subgroup than the HER2 negative group, and its inhibitor could prevent the agonistic tumor-promoting activity of tamoxifen and restore its estrogen antagonist properties against ER/HER2- positive xenograft tumors in mice." (PMID 34879004, 2021). "Tumor FASN expression did not significantly differ by PTEN tumor status (p = 0.25)." (PMID 33166087, 2021).
tumor (continued). "Similarly, tumor cells also secrete different molecules that significantly impact the TME and tumor metabolism and could account for the enhanced expression of FASN expression in LECs." (PMID 34831316, 2021). "We previously demonstrated that FASN inhibitors such as C75 operate as bona fide anti-estrogens, likely by alleviating AKT cross-inhibition of ERK and feeding signaling loops that boost a non-genomic ERα/MAPK cross-talk capable of transactivate ERα-driven tumor suppressive responses." (PMID 33800852, 2021). "Furthermore, the values for uGCP were stratified according to the TNM classification, tumor grading, UICC stage, and Laurén’s classification, with significantly lower values for the FASN mRNA in patients with tumors grading G3 as compared to patients with G1–2." (PMID 34885085, 2021). "Not all tumor cells are adversely affected by FASN inhibition." (PMID 32872164, 2020). "Interestingly, statistical analysis via Spearman Correlation showed a positive correlation between expression of CD36 and FASN in primary CRC tumor tissues, but it was not statistically significant (Spearman r = 0.21743, n = 56)." (PMID 32850342, 2020). "The effectiveness of the FASNi GSK2194069 against breast and prostate cancer cells was significantly compromised if macropinocytic cells had access to necrotic cell debris; if fatty acids can be scavenged from the tumor microenvironment, cells will no longer be dependent on FASN." (PMID 32111826, 2020). "Further, up-regulation of fatty-acid synthase (FASN) by M-CSF in tumor infiltrating myeloid cells was required for PPARβ/δ-dependent expression of immunosuppressive and pro-angiogenic genes (e.g. IL-10, Arg1 and VEGF) and consequent promotion of tumor progression, in a model of Lewis lung cancer." (PMID 31535085, 2019). "Compared to vector-expressing cells, overexpression of FASN (FASN) did not increase signal in the primary tumor in vivo but did lead to significantly higher signal in the whole mouse and femurs, indicating that FASN overexpression promotes metastasis of PC3-Luc cells." (PMID 31831821, 2019). "These could help to identify new markers beside mTOR activity characterisation—such as FASN, CPT1a, ACSS2—or find good mitochondrial function markers (e.g. TOM20, NRF1), and to assign the metabolic expression profile of tumours before starting treatments in patients." (PMID 30574020, 2018). "Together, these findings suggest that TVB-3664 as a monotherapy has anti-tumor activity in CRC; however, studies with a larger number of cases are required to establish reliable biomarkers to identify a population of patients that is sensitive to FASN-targeted therapy." (PMID 29872506, 2018). "Western blotting revealed that FASN protein expression was elevated in CRC tissues, while real-time PCR and Western blotting indicated that FABP1, CD36 and Caveolin-1 mRNA and protein levels were reduced in CRC, potentially due to the reduced availability of exogenous lipids for the tumor." (PMID 28938608, 2017). "Thus, the present findings indicate that c-Met upregulation hastens tumor development in AKT-injected hepatocytes albeit without rendering these cells resistant to FASN depletion." (PMID 26857837, 2016). "However, double knockdown of P300 and FASN had little or no further inhibition of C4-2 tumor growth in mice." (PMID 26934656, 2016). "Similarly, the expression of FASN was higher in xenograft tumours of the HFD group than the LFD group, whereas the mean serum FASN level was significantly lower in the HFD group than in the LFD group (3344.6±1005.8 and 6666.4±3685.8 pg/ml, respectively, P=0.026)." (PMID 26878389, 2016). "However, effects on tumor cell growth of combining a FASN inhibitor and a chemotherapeutic drug were not investigated." (PMID 25947066, 2015). "Co-expression of FASN and HER2 might be a sign of poor prognosis tumor." (PMID 25433947, 2015). "This suggested that FASN and HER2 might have a mutual role in triggering the tumor." (PMID 25433947, 2015).
tumor (continued). "Although initially the inhibitory properties of orlistat were demonstrated for pancreatic lipase, a large survey of a number of tumor and normal cell lines has lead to the conclusion that orlistat has no other targets than FASN in tumor cells, and that has minimal effects on the normal cells." (PMID 23029529, 2012). "Of note, FASN expression was more intense in the non-keratinizing poorly differentiated tumors with basaloid morphology, where p63 was found to be positive in almost 100% of tumor cells." (PMID 19517019, 2009). "Studies suggest that targeting lipid metabolism pathways, such as inhibition of fatty acid synthase (FASN) or acyl-CoA synthetase long-chain family member 4 (ACSL4), could promote ICD by increasing lipid peroxidation and enhancing the immunogenicity of tumor cells." (PMID 40299564, 2025). "However, aside from FASN, other enzymes involved in de novo FA synthesis also play an instrumental part in tumour progression, such as ACC, the rate-limiting enzyme for de novo FA synthesis, and ACLY, which provides glucose-derived acetyl-CoA as the main substrate for both ACC and FASN." (PMID 35448537, 2022). "Of note, recent reports suggest that the tumor-supporting activity of FASN might be mediated predominantly by its ability to induce genes involved in proliferation and inhibition of apoptosis, rather than by FASN lipid biosynthesis properties." (PMID 33187130, 2020). "It is unclear why there was not good concordance for FASN, GSK3b and NCad, but directional discordance between mRNA and protein for any given gene is not an unanticipated finding, and on an individual gene level, is more discordant in tumor versus cognate normal tissue." (PMID 31881020, 2019). "Similar to LIM2405, which was not sensitive to FASN inhibition due to very low expression of the enzyme in this cell line, low levels of FASN expression in Pt 2377PT and LM PDXs were associated with resistance to TVB-3664 and prolonged treatment led to acceleration of tumor growth." (PMID 29872506, 2018). "In those studies, mTORC1 inhibitors, Pak inhibitors, celecoxib (cox 2 inhibitor), and cerulenin (fatty acid synthase inhibitor) were shown to slow tumor growth significantly compared to their respective control, yet none of the drugs successfully prevented progressive tumor growth." (PMID 29207619, 2017). "Additionally, the mechanisms how FASN inhibition affects tumor progression is not yet adequately addressed and therefore elucidation of the mechanisms is required to understand the significance of FASN inhibition and encourage utilization of FASN-targeted therapy." (PMID 23741342, 2013). "Moreover, in a number of well- to moderately-differentiated HNSCCs, p63 and FASN tended to co-localize in the least differentiated cells at the periphery of the lesion while more differentiated cells in the central part of the tumor nodules were mostly negative for the expression of both proteins." (PMID 19517019, 2009). "Conversely, protein levels of these enzymes (e.g. FASN, DPP4, PREP, ELANE) showed only weak or no changes between tumors and nontumor adjacent-tissues, resulting in substantially less accurate tumor classification (right)." (PMID 40425563, 2025). "However, FASN-dependent endogenous synthesis of FAs is not a common feature of all liver tumors, the development of iCCA is not sensitive to a lack of FASN, and tumor growth is dependent mainly on exogenous FA uptake, suggesting that inhibition of exogenous FA uptake may be a new therapy for iCCA." (PMID 39984452, 2025). "Fatty acid synthase (FASN)-mediated de novo fatty acid synthesis contributes to the functional maturation of Treg cells, and the absence of FASN in Treg cells inhibits tumor growth." (PMID 39588377, 2024). "Real time PCR and Western blot analysis data showed that the expression of ACC1, but not ACSL1 and FASN was significantly increased in TDM, BMDM and in HCC tumor tissue with B. thetaiotaomicron or acetic acid treatment." (PMID 38270111, 2024).
tumor (continued). "Statistical analysis of correlation between FASN and CD36 revealed a significant negative correlation between FASN and CD36 mRNA levels in tumor tissues, but not in normal tissues." (PMID 32850342, 2020). "Furthermore, recent studies demonstrate that, in addition to autophagy, p62 plays a crucial role in a number of cellular processes related to malignant transformation and tumor progression; therefore, FASN-induced accumulation of p62 may also be independent of autophagy in the progression of CRC." (PMID 25970773, 2015). "However, PET imaging has not been used for characterization of changes in tumor metabolism resulting from orlistat-induced inhibition of FASN due to uncertainty of pharmacodynamic changes in metabolic pools and signal transduction pathways that could serve as biomarkers of treatment response." (PMID 22886728, 2013). "Regardless of mechanism, these data show that fatty-acid synthase (FAS) inhibitors are more toxic at acidic pH, such as that encountered in tumors, and this may be reflected in their strong anti-tumor activity." (PMID 35545051, 2022). "Several enzymes involved in these synthesis pathways, including FASN, ACLY, ACCs, choline kinase, monoglyceride lipase, and HMGCR have been ascribed critical roles in oncogenesis or tumor progression in vivo, yet have not been tested in clinical settings." (PMID 29434587, 2018). "Furthermore, it suggests FASN activity need not be completely inhibited; instead, novel therapeutics that influence the spectrum of products produced by FASN may be sufficient to alter tumor properties such as signaling pathway activation, cell proliferation, and metastasis." (PMID 25472762, 2014). "Similarly, while the expression levels of ACLY, FASN, ACSL1, and ACSL5 in the liver tissues were decreased in C26 tumor-bearing mice compared with control mice without tumors, their expression levels were significantly increased in the liver tissues of the mice fed with a fenofibrate diet." (PMID 38245529, 2024).
infection (57 papers, 2009 to 2025). The state of being infected such as from the introduction of a foreign agent such as serum, vaccine, antigenic substance or organism. "Fatty acid synthase (FASN), the key enzyme regulating de novo biosynthesis of fatty acids, is crucial for the lethal infection of fungi; however, its pathogenic mechanism is still far from clear." (PMID 40138332, 2025). "Consistent with the EBV-induced upregulation of FASN during infection, low enough concentrations of palmitate (25μM) promoted LCL growth." (PMID 40403013, 2025). "Our findings support the notion that HSV-1 directly modulates FASN expression to promote de novo lipogenesis during infection." (PMID 40327680, 2025). "Though BoAHV-1 productive infection leads to depletion of FASN, FASN still plays an important role in viral productive infection, as demonstrated using both siRNAs and chemical inhibitors." (PMID 41196069, 2025). "Compared to the control, FASN protein levels decreased to approximately 68.85%, 8.42%, and 7.6% after infection for 24, 36, and 48 h, respectively." (PMID 41196069, 2025). "With the EGFP- tagged constructs, no colocalization was observed between ZIKV-NS5 and FASN or between DENV-NS5 and FASN (consistent with the results seen in natural infection)." (PMID 40131913, 2025). "The roles of FASN in BoAHV-1 productive infection were analyzed in MDBK cells using FASN-specific siRNAs." (PMID 41196069, 2025). "Subsequent Western blot analysis and activity assay provided further confirmation of FASN induction during the progression of infection, indicating an upregulation of lipogenesis." (PMID 40327680, 2025). "A proteomic and lipidomic analysis of HCV-infected cells revealed that infection increased FASN and lipogenic enzymes involved in peroxisomal and mitochondrial fatty acid oxidation." (PMID 40558086, 2025). "In the next section, we review the cellular regulation and mechanism of FASN and discuss how viruses take advantage of its enzymatic function during infection." (PMID 40558086, 2025). "Infection with HSV-1 increases fatty acid synthase (FASN) expression, resulting in increased lipid production and altered lipid distribution." (PMID 40327680, 2025). "Collectively, studies using both siRNAs and chemical inhibitors consistently support this conclusion that FASN plays a crucial role in BoAHV-1 productive infection in MDBK cells." (PMID 41196069, 2025). "The decreased FASN protein expression observed during BoAHV-1 productive infection in both MDBK and Neuro-2A cells is consistent with that observed in TG neurons during viral lytic infection." (PMID 41196069, 2025). "Quantitative analysis revealed that the proportion of FASN+ neurons, including both cytoplasmic and nuclear staining, was 43.80%, 10.06%, and 21.55% in calves with mock infection, acute infection, and latency, respectively." (PMID 41196069, 2025). "Here, we provide evidence that FASN also plays a significant role in the infection of BoAHV-1, a member of the alphaherpesvirus family." (PMID 41196069, 2025). "Similar to that observed in CVB3-infected HeLa cells, full-length FASN protein levels decreased, and a stable product was detected as infection progresses." (PMID 38953667, 2024). "Immunohistochemistry revealed that infection with S. mansoni reduced parenchymal fatty acid synthase expression with the exception of perigranulomatous hepatocytes." (PMID 36590323, 2022). "The EBV-encoded transcription factor EBNA2 is produced early in the infection phase (72 h), and the cholesterol and fatty acid synthesis pathways, including upregulation of FASN, were found to be induced early in infection (96 h)." (PMID 33208446, 2021). "To evaluate the relative contribution of FAs from the FASN-dependent de novo synthesis and those released from lipid droplets, we blocked them individually and assessed the activation of PC synthesis upon infection." (PMID 30148882, 2018).